RN7SL452P (RNA, 7SL, cytoplasmic 452, pseudogene)
Gene: Miscellaneous RNA gene on chromosome 14 (50,637,691 to 50,637,981, reverse strand). Ensembl gene ENSG00000243103.
Homologues: Orthologues: chimpanzee Metazoa_SRP (98% identical), macaque Metazoa_SRP (88% identical). Paralogues in human: RN7SL1 (81% identical), RN7SL2 (80% identical), RN7SL3 (80% identical), RN7SL296P (79% identical), RN7SL655P (79% identical), RN7SL45P (78% identical), RN7SL566P (78% identical), RN7SL220P (78% identical), RN7SL478P (78% identical), RN7SL118P (77% identical), RN7SL378P (77% identical), RN7SL322P (77% identical), and 705 more.